G6PD (glucose-6-phosphate dehydrogenase)
Diseases named in the same sentence as G6PD in open-access papers (continued):
Sharing a sentence is not in itself a finding about the gene and the disease.
hepatocellular carcinoma (continued). "Later on, analysis of intracellular G6PD activity in various cancer cell lines, such as human cervical carcinomas, esophageal carcinomas, hepatomas, lung adenocarcinomas, and colon adenocarcinomas, revealed that G6PD was particularly overexpressed in human esophageal cancer cell lines." (PMID 28553614, 2017). "Similarly, survival probability in hepatocellular carcinoma was reliably predicted by a glioma prediction model (ACSL3, ACSL6, ACACA, G6PD, SLC1A5, SLC7A11 and VDAC2) and by a risk model with a strong overlap with the genes in the glioma models (G6PD, HMOX1, LOX, SLC7A11, STMN1/Stathmin 1)." (PMID 34926298, 2021). "Suppression of G6PD induces cellular senescence in hepatocellular carcinoma (HCC) cells and leads to intracellular oxidative stress, making cancer cells sensitive to chemotherapy." (PMID 32582032, 2020). "However, G6PD regulation is still not completely understood in hepatocellular carcinoma." (PMID 29904144, 2018). "This study uncovers the therapeutic mechanism of RRx-001 in hepatocellular carcinoma (HCC): by inhibiting G6PD, it reduces NADPH levels, leading to redox imbalance and F-actin contraction, thereby inducing disulfidptosis-a process that can be partially reversed by TCEP." (PMID 41888099, 2026). "For example, in hepatocellular carcinoma, high expression of METTL3 was positively correlated with G6PD expression, and patients with low expression of METTL3 and high expression of G6PD had a relatively better prognosis." (PMID 40458727, 2025). "G6PD exhibited the most significant prognostic value in our survival analysis and Cox regression model, indicating its crucial role in hepatocellular carcinoma (HCC) progression." (PMID 40116585, 2025). "Among the prognostically characterized aging genes, EZH2, G6PD, LGALS3 and PSMD14 were significantly differentially expressed in hepatocellular carcinoma samples from the TCGA database." (PMID 37853322, 2023). "A previous study revealed that 3 ferroptosis-related genes (SLC7A11, G6PD, CISD1) in hepatocellular carcinoma were upregulated in tumor tissue, and their high expression correlated with a poor prognosis." (PMID 33672990, 2021). "In hepatocellular carcinoma cell models, BAG3 protein directly interacts with G6PD by inhibiting G6PD dimerization and activity." (PMID 31500396, 2019). "As a rate‐limiting enzyme in PPP, G6PD participates in glucose utilization by catalysing the first step of the PPP in a variety of cancer cells, including the A375 melanoma cell line and the Hep3B hepatocellular carcinoma line." (PMID 33630390, 2021). "G6PD could activate the STAT3 pathway to induce the EMT process and further promote the migration and invasion of hepatocellular carcinoma cells." (PMID 29954422, 2018). "In rat experimental models consisting of normal and regenerating livers and cell lines, G6PD activity was found to be highly increased in the Novikoff hepatoma and in eight rapidly growing hepatomas, but not in the one displaying a slow growth rate." (PMID 28553614, 2017). "In addition, it has been shown that the expression of cytochrome P450 oxidoreductase (POR), a positive regulator of ferroptosis, is significantly increased in G6PD knockdown hepatocellular carcinoma (HCC) cells, which suggests that G6PD may inhibit ferroptosis through POR." (PMID 36091812, 2022). "It is reported that in the prognosis model of hepatocellular carcinoma, the genes (NFS1, CISD1, ACSL3, NQO1, SLC7A11, GPX4) that can protect hepatocytes with ferroptosis and the genes (ACACA, CARS, G6PD, SLC1A5) that induce ferroptosis are all up-regulated in HCC, and are related to poor prognosis." (PMID 36387286, 2022). "To determine the association of the PPP and SGS pathways in clinical HCC, we analysed PHGDH, PSAT1 and G6PD RNA expression in HCC tumour and non-tumour liver tissue from the Cancer Genome Atlas (TCGA) liver hepatocellular carcinoma (LIHC) database." (PMID 33028928, 2020).
sickle cell disease (57 papers, 2005 to 2025). Sickle cell anemias are chronic hemolytic diseases that may induce three types of acute accidents: severe anemia, severe bacterial infections, and ischemic vasoocclusive accidents (VOA) caused by sickle-shaped red blood cells obstructing small blood vessels and capillaries. "Diabetic acidosis promotes the occurrence of hemolytic anemia in patients with congenital deficiency of glucose-6-phosphate dehydrogenase or in sickle cell anemia." (PMID 34708130, 2021). "Again, 22% out of 41 sickle cell anaemia patients were found to be G6PD-deficient in Lubumbashi, Zaire." (PMID 31016042, 2019). "Poverty, malnutrition, and genetic predispositions to sickle cell disease and glucose-6-phosphatase dehydrogenase (G6PD) deficiencies, for example, are common in the study area." (PMID 27633035, 2016). "Sickle cell anemia, deficiency of glucose-6-phosphate dehydrogenase (G6PD ) and α and β thalassemia are the result of polymorphisms that confer partial protection against infection by Plasmodium falciparum." (PMID 24893190, 2012). "This may show up in individuals with higher underlying oxidative stress, such as newborns, people with sickle cell disease, and those using oxidative drugs, as well as lower post-transfusion reactivity of stored G6PD-deficient RBCs and decreased transfusion efficacy in patients." (PMID 40367898, 2025). "The induction of an increase in the G6PD activity was an important effect of HU since patients with sickle cell anemia have a restricted flow of NADPH." (PMID 34679734, 2021). "Sickle cell disease was the most commonly reported (64.5%) genetic disease followed by G6PD (51.1%), Down syndrome (29.3%), and some other sporadic disorders." (PMID 35047260, 2021). "Some studies suggest the Mediterranean G6PDS188F variant makes no contribution to sickle cell anemia–associated PH, while others suggest the frequency of G6PD mutation is higher among idiopathic PH patients than the general population." (PMID 36372233, 2022). "While previous studies suggest G6PDS188F variant makes no contribution to sickle cell anemia–associated PH, others suggest the frequency of G6PD mutation is higher among idiopathic PH patients than the general population." (PMID 36372233, 2022). "Increased G6PD activities enhance the production of NADPH and this might help to lessen the clinical effects caused by sickle cell anemia." (PMID 34679734, 2021). "Other authors, however, do not agree with this association, believing rather that the mutated genes responsible for both the G6PD and the sickle cell disease do not stay on the same chromosome, so they cannot be linked together." (PMID 31016042, 2019). "The prevalence of sickle cell disease was 6%, 2% for β-thalassemia and 25% for G6PD." (PMID 24742222, 2014). "In addition, other conditions and genetic disorders such as sickle cell anaemia and G6PD, which may influence the diagnostic utility of ZPP, were not studied." (PMID 25428714, 2014). "In Jamaica, difference in G6PD status did not affect the total haemoglobin concentration, reticulocyte count, unconjugated serum bilirubin, Hb F concentration, plasma haemoglobin concentration and frequencies of clinical severity and of leg ulceration in patients with sickle cell disease." (PMID 24568147, 2014).
lung carcinoma (54 papers, 2013 to 2025). "This emphasizes that oncogenic events play a crucial role in determining the dependence and associated mechanisms of distinct subtypes of KRAS-driven lung cancer on G6PD." (PMID 38997257, 2024). "Increased G6PD expression has been linked to poor prognosis and resistance to chemotherapy in breast, colorectal, and lung carcinomas." (PMID 38256136, 2024). "As G6PD showed the highest risk coefficient for lung cancer, the impact of G6PD downregulation on lung cancer cell proliferation and colony formation was investigated." (PMID 37315289, 2023). "G6PD-deficient colon and lung cancer cells increase malic enzyme and isocitrate dehydrogenase activity." (PMID 35110412, 2022). "Thus, oncogenic driver mutations determine lung cancer dependence on G6PD, whose targeting is a potential therapeutic strategy for tumors harboring KRAS and LKB1 co-mutations." (PMID 38997257, 2024). "To determine whether G6PD glycosylation is associated with lung cancer progression, we analysed the level of glycosylation in the previous 16 paired samples according to their stages." (PMID 26399441, 2015). "In conclusion, overcoming cisplatin resistance through inhibition of G6PD could improve the understanding of the mechanisms underlying cisplatin-induced resistance in human lung cancer and may provide insights into the therapeutic potential of this treatment to combat resistance." (PMID 29445340, 2018). "Bioinformatic data from studies on FOXO signaling indicate that glucose-6-phosphate dehydrogenase (G6PD), a key enzyme in the pentose phosphate pathway, is central to cellular processes in lung cancer tissues." (PMID 40642746, 2025). "Glucose-6-phosphate dehydrogenase (G6PD), the rate-limiting enzyme, regulates NADPH/NADP + ratios and is implicated in tumorigenesis, particularly in KRAS-driven, LKB1-deficient lung cancer." (PMID 40734168, 2025). "Based on the results, it was concluded that M. procera inhibited G6PD as part of its anticancer mechanism against A549 lung cancer cells." (PMID 40142097, 2025). "G6PD glycosylation is enhanced in lung cancer, and G6PD activity modulation is a promising therapeutic strategy for lung cancer." (PMID 38194707, 2024). "O-GlcNAcylation of G6PD facilitates lung cancer while phosphorylation of G6PD by polo-like kinase 1 (Plk1) affects cell cycle progression and cell proliferation of multiple cancers." (PMID 39337387, 2024). "This also underscores the need for personalized therapies tailored to different subgroups of KRAS-driven lung cancers, especially when considering the application of G6PD inhibitors in cancer treatment." (PMID 38997257, 2024). "In this study, by using GEMMs of KRAS-driven NSCLC, we found that the dependence on G6PD is distinct in different subtypes of lung cancer." (PMID 38997257, 2024). "Previous studies have shown that both G6PD and PDK1 are associated with cisplatin resistance in lung cancer and that their inhibition or downregulation can sensitize cancer cells to cisplatin treatment." (PMID 38351531, 2024). "Treatment with G6PD inhibitors has been shown to effectively reduce G6PD expression in lung cancer cells, resulting in a significant inhibition of their proliferative capacity." (PMID 38685115, 2024). "Immunohistochemistry was employed to examine the distribution of immune cells in G6PD knockout nude mice model of PAH complicated with lung cancer." (PMID 38194707, 2024).
lung carcinoma (continued). "We will collect the blood and tissues of lung cancer patients at different stages for G6PD detection and analysis, and detect which stage of the development of LUAD is more important for G6PD expression." (PMID 38194707, 2024). "In our previous work, it was found that the tyrosine metabolizing enzyme HPD regulates the expression of G6PD, mediates the pentose phosphate pathway, and regulates glucose metabolic flux and DNA synthesis in lung cancer." (PMID 37786553, 2023). "For instance, in colon and lung cancer, inhibition of G6PD, the rate-limiting enzyme in the PPP, can reverse cisplatin resistance." (PMID 37611829, 2023). "Results from Ki67 staining and colony formation assays demonstrated that interfering with G6PD can substantially inhibit the proliferation ability of lung cancer cells." (PMID 37315289, 2023). "A recent study showed that KRT6A promotes growth and invasion of lung cancer cells by regulating glucose-6-phosphate dehydrogenase expression through MYC." (PMID 36275729, 2022). "G6PD activity is increased in several cancer types, including esophageal, gastric, colorectal, bladder, breast, and lung cancers." (PMID 34819088, 2021). "The finding that G6PD O-GlcNAcylation is important for A549 lung cancer cell proliferation and tumor growth prompted us to examine G6PD glycosylation in human lung cancers." (PMID 26399441, 2015). "G6PD knock down A549 lung carcinoma cells, together with the common pathogen Staphylococcus aureus, were employed in our cell infection model." (PMID 24223971, 2013). "Additionally, the extracts were tested for their effects on the proliferation of human lung cancer cells (A549), revealing that M. procera achieved a 94% inhibition of G6PD and demonstrated cytotoxic effects against A549 cells." (PMID 40142097, 2025). "M. procera inhibited G6PD as part of its anticancer mechanism against A549 lung cancer cells." (PMID 40142097, 2025). "Furthermore, patients with low G6PD expression undergoing immune checkpoint inhibitor therapy for lung cancer and melanoma have better prognoses." (PMID 40533802, 2025). "Hence, our study also proposes an innovative therapeutic approach for treating KL lung cancer by combining G6PD inhibitors with a serine/glycine depletion diet." (PMID 38997257, 2024). "In contrast to KP lung cancers, G6PD showed greater functional importance in KL lung cancers." (PMID 38997257, 2024). "Furthermore, G6PD O-GlcNAcylation is elevated in human lung cancers, and blocking O-GlcNAc on G6PD reduces cancer cell proliferation and tumour growth." (PMID 39474868, 2024). "Treatment with G6PD inhibitor G6PDi effectively reduced G6PD expression in lung cancer cells." (PMID 37315289, 2023). "Treatment with G6PD inhibitor effectively reduced G6PD expression in lung cancer cells and substantially inhibited the proliferation ability of lung cancer cells, which showed the first time of the adverse prognostic significance and pro-carcinogenesis effect of G6PD in LUAD." (PMID 37315289, 2023). "In cisplatin-resistant A549 lung cancer cells, the expression of G6PD, a key enzyme involved in bypassing the pentose phosphate pathway, was increased, and reducing G6PD could increase cisplatin sensitivity." (PMID 34250022, 2021). "In this study, the effect of 6-AN, a competitive G6PD inhibitor, was explored in lung cancer cells." (PMID 34827081, 2021). "G6PD is dynamically modified by O-GlcNAc and glycosylated in lung cancers." (PMID 33251387, 2020). "Thus, this study reveals HPD as a novel regulator of LKB1–AMPK signaling-mediated HDAC10 nuclear location, which contributes to G6PD expression in promoting tumor growth, which is a promising target for lung cancer treatment." (PMID 31285420, 2019).
lung carcinoma (continued). "Moreover, exogenous expression of HPD significantly increased the G6PD enzyme activity, mRNA level and protein level in H1299, H226 lung cancer cells and 293T cells." (PMID 31285420, 2019). "In recent years, more and more research groups have paid attention to the important role of G6PD in various cancer cells, including colorectal cancer, cervical cancer, renal cell carcinoma, esophageal squamous cell carcinoma, lung cancer and head and neck cancer." (PMID 29445340, 2018). "We obtained a total of 39 pairs of primary human lung cancer tissue samples with matched adjacent normal lung tissues, and determined the level of glycosylation by the chemoenzymatic tagging approach and normalization to G6PD protein levels." (PMID 26399441, 2015). "To create a system to study the effect of G6PD S84 glycosylation on cellular metabolism, we depleted endogenous G6PD and stably expressed small hairpin RNA (shRNA)-resistant Flag-tagged WT or S84V G6PD in A549 lung cancer cells (henceforth referred to as WT G6PD or S84V G6PD replacement cells)." (PMID 26399441, 2015). "Therefore, it is crucial to discover and develop G6PD inhibitors from mushrooms, such as M. procera, as they may be ideal treatment options for lung cancer." (PMID 40142097, 2025). "Besides, the upregulation of G6PD has been observed in lung cancer and colorectal cancer." (PMID 39516455, 2024). "Since G6PD had the highest risk factor of LUAD, we further verified the protein expression of G6PD in LUAD cells by western blot, and confirmed through colony formation experiment that interference with G6PD can significantly inhibit the proliferation ability of lung cancer cells." (PMID 37315289, 2023). "Indeed, we found that AMPK activity is not affected by HPD, nor was G6PD expression in LKB1-deficient lung cancer cells." (PMID 31285420, 2019). "Glucose-6-phosphate dehydrogenase (G6PD), the rate-limiting enzyme of the pentose phosphate pathway, was found to be modified and activated by O-GlcNAcylation in response to hypoxia, and the level of O-GlcNAcylated G6PD was higher in lung cancers than in matching normal lung tissue." (PMID 30123425, 2018). "Importantly, G6PD glycosylation is elevated in human lung cancers." (PMID 26399441, 2015). "Importantly, G6PD glycosylation is increased in human lung cancers." (PMID 26399441, 2015). "Thus, the increased G6PD glycosylation correlates with the increased OGT expression in lung cancer." (PMID 26399441, 2015). "It reported that the levels of G6PD were increased significantly in all stages (I, II, III and IV) of lung cancer when compared with the normal tissues." (PMID 38194707, 2024). "Previous research has indicated that METTL14-binding peaks near the G6PD 3’-UTR regions can undergo methylation, thereby promoting translation facilitated by m6A ‘readers’ such as YTHDF2, which in turn enhances lung cancer cell growth." (PMID 39138186, 2024). "HPD contributes to G6PD expression, thus enhancing the PPP flux and facilitating lung cancer growth." (PMID 39025830, 2024). "Results indicated a significant downregulation of CX3CL1, MS4A15, and GSTA1 in lung cancer cells, while EPS8L3, G6PD, KRT6A, and S100P were notably upregulated, in line with the bioinformatics analysis findings." (PMID 37315289, 2023). "In human lung cancer A549 cells, decreased sirtuin 2(SIRT2) reduces the expression and activity of glucose-6-phosphate dehydrogenase (G6PD) by acetylation, resulting in enhanced production of ROS and IAV replication." (PMID 35967412, 2022). "KRT6A regulates the expression of G6PD through c-MYC/MYCN to promote the proliferation and invasion of lung cancer cells." (PMID 34235156, 2021). "Inhibition of the PPP and silencing of two PPP enzymes, glucose-6-phosphate dehydrogenase (G6PD) and phosphoglycerate dehydrogenase (PGD), hinders erastin-induced ferroptosis in human lung cancer cells." (PMID 33868986, 2021).